TNF (tumor necrosis factor)
Diseases named in the same sentence as TNF in open-access papers (continued):
Sharing a sentence is not in itself a finding about the gene and the disease.
Cognitive impairment (continued). "These cognitive deficits are thought to be driven by chronic hypoxemia and impaired cerebral perfusion, systemic inflammation involving IL-6, TNF-α and CRP, and cardiovascular comorbidities frequently coexisting in COPD." (PMID 41598607, 2026). "In this regard, a relevant observation is the consistency of the elevation of inflammatory cytokines IL-6, IL-13, IL-8, IL-1β, and TNFα at the longest phase of follow-up related to cognitive deficits and/or post-acute sequelae." (PMID 41516418, 2026). "Due to the significant differences in the levels of VCAM‐1 and TNF‐α among groups, the effect of VCAM‐1 and TNF‐α on cognitive impairment was examined through mediation analysis." (PMID 39829127, 2025). "While associations between elevated inflammatory markers (e.g., IL-6, TNF-α) and cognitive impairments have been observed, direct evidence establishing neuroinflammation as a primary cause of LDs is still limited." (PMID 40150106, 2025). "One of the biomarkers that showed significant differences between Alzheimer’s disease, mild cognitive impairment, and control groups was TNF-α." (PMID 40711681, 2025). "Ursolic acid can also inhibit the activation of microglia and astrocytes and reduce the levels of TNF–α, IL–1β, and IL–6 in the brain inflammation of mice with lipopolysaccharide–induced cognitive deficits." (PMID 40005889, 2025). "Increased levels of serum TNF-α and IL-1β correlate with an accelerated rate of cognitive impairment in AD patients." (PMID 40847374, 2025). "Specifically, we observed increased levels of the pro-inflammatory cytokines IL-6, TNF-α, and CXCL1, all of which have been implicated in cognitive impairments associated with AD." (PMID 41282256, 2025). "A recurring finding was the elevation of pro-inflammatory cytokines (i.e., IL-1β, IL-6, TNF-α) together with reduced BDNF levels, frequently associated with cognitive deficits in both healthy and tumor-bearing models." (PMID 41155372, 2025). "Hypoxia promoted hippocampal neurogenesis and suppressed amyloid β (Aβ) plaque formation and pro-inflammatory tumor necrosis factor α expression in rat models of cognitive impairment." (PMID 41301754, 2025). "When comparing studies using chemotherapy in healthy versus tumor-bearing animal models, both groups exhibited a consistent pattern of cognitive impairment accompanied by increased levels of pro-inflammatory cytokines, particularly IL-1β, IL-6, and TNF-α." (PMID 41155372, 2025). "This study demonstrates that prenatal valproic acid (VPA) exposure induces gut microbiota dysbiosis (Bacteroidia↓), exacerbating neuroinflammation (↑IL-1β/IL-6/TNF-α) and cognitive deficits in offspring via the microbiota-gut-brain axis." (PMID 40881681, 2025). "These microbial shifts are associated with increased neuroinflammatory cytokines, such as interleukin-1β (IL-1β), interleukin-6 (IL-6), and tumor necrosis factor-alpha (TNF-α), which have been implicated in synaptic plasticity and cognitive deficits." (PMID 40881681, 2025). "Beyond well studied CRP, IL-6 and TNF-α, literature on other chemokines is sparser and mainly focus on clinically defined AD or mild cognitive impairment (MCI)." (PMID 39824904, 2025). "The inflammatory factor TNF-α, which plays a role in this process, can initiate a peripheral cytokine release cascade, leading to cognitive impairment." (PMID 39997934, 2025). "TNF-α and IL-1β appear to play a significant role in cognitive decline in patients with Alzheimer’s disease and mild cognitive impairment, showing potential to distinguish between different stages of Alzheimer’s." (PMID 40711681, 2025). "It was reported that the plasma level of either TNF RI or TNF RII was higher in patients with mild cognitive impairments (MCI) (n = 137) than in age-matched controls (n = 30)." (PMID 41153321, 2025).
Cognitive impairment (continued). "Changes in hippocampal neuroinflammatory markers were correlated with cognitive impairments (CA1: TNF-α, NF-κB1, IL-1β; DG: TNF-α, NF-κB1) and social deficits (CA1: TNF-α,IL-1β; DG: TNF-α, NF-κB1)." (PMID 40859005, 2025). "TNF-α is a proinflammatory cytokine that mediates neuroinflammation and contributes to cognitive impairment in conditions such as AD." (PMID 40151497, 2025). "Our findings showed that treatment with apigenin alleviates cognitive impairment by reducing TNF-α and IL-6 levels in VPA-treated rats." (PMID 39720795, 2024). "The mice exhibited cognitive impairment accompanied by increased expression of proinflammatory factors (IL-1β, TNF-α), proapoptotic molecules (caspase-3, bax) and microglial activation in the hippocampus 1, 3 and 7 days after surgery." (PMID 37973625, 2024). "Neuroinflammation featured by the overactivation of glial cells, robustly produced a body of neuroinflammatory factors, including TNF‐α, IL‐6, IL‐1β and NO, etc., and subsequently led to neuronal damage and cognitive impairment." (PMID 37697966, 2024). "When exposed to specific proinflammatory factors: IL-1α, TNF-α and C1q, astrocytes can turn to A1 neurotoxic phenotype and further contribute to cognitive deficits in Alzheimer’s disease (AD)." (PMID 38427092, 2024). "Blocking TNFα also prevented the alterations in AMPA and NMDA receptors associated with cognitive deficits in hyperammonemic rats." (PMID 39698415, 2024). "TNF-α is the main pro-inflammatory cytokine in IBD pathology, and in people with Alzheimer’s disease, increased serum levels of TNF-α exacerbate cognitive impairment and neurodegeneration through activation of microglia." (PMID 39064809, 2024). "Activating microglia, enhancing the expression of TNF-α and IL-1β in vitro, and resulted in cognitive impairment, Aβ deposition and Tau hyperphosphorylation in the mouse cerebrum." (PMID 38362505, 2024). "Cognitive impairment has been closely linked to inflammation, as shown by elevated levels of C-reactive protein (CRP), interleukin (IL)-6, and tumor necrosis factor (TNF)-α in affected individuals." (PMID 39118546, 2024). "TNF-α and MMP-9 are pro-inflammatory cytokines and proteases, respectively, which have been implicated in the pathophysiology of cognitive impairment." (PMID 39135795, 2024). "Given that TNF-α PGS, structural connectome alterations, and cognitive deficits have been particularly linked to current depressive symptomatology, we assume these associations to be most pronounced in acutely depressed patients." (PMID 38693319, 2024). "Several epidemiological studies consistently demonstrate a significant association between systemic inflammatory markers, namely C-reactive protein (CRP) and tumor necrosis factor-α (TNF-α), and cognitive impairment or dementia." (PMID 39114530, 2024). "This is surprising as postsurgical studies in elderly patients found plasma TNFα, IL-6, and IL-10 levels to be independent predictors for adverse central postoperative outcomes such as cognitive deficits." (PMID 38585987, 2024). "Consistent with our results, sitagliptin (600 mg/kg/day, 90 days, PO) reduced cognitive impairment and brain damage in rats suffering from chronic cerebral hypo-perfusion by decreasing inflammation via attenuating IL-1β, TNF-α, and other inflammatory factors." (PMID 38333747, 2024). "In elderly patients with constipation, the relative abundance of Blautia reduced, while Blautia was positively correlated with mild cognitive impairment and negatively correlated with TNF-α, IL-6, and IL-1β, which was consistent with our results." (PMID 38398836, 2024). "Several anti-inflammatory treatments targeting microglial activation have been shown to significantly decrease TNFα expression, reducing synaptic dysfunction and cognitive impairment in AD." (PMID 39712494, 2024).
Cognitive impairment (continued). "The activation of astrocytes and microglia has been widely acknowledged to contribute to cognitive impairment through the release of proinflammatory mediators, including IL-1β and TNF-α." (PMID 38991663, 2024). "In the AD and mild cognitive impairment (MCI) groups, IL-6 and TNF-a were likewise positively associated." (PMID 38230738, 2024). "Another TNF-α inhibitors, Adalimumab reduces AD pathology and neurotoxicity by inhibition of NF-κB and improves cognitive deficits." (PMID 38659577, 2024). "We noticed that cytokines IL-1β, TNF-α and IL-6 changes were rapid but transient, while C3 upregulation was delayed but prolonged, a pattern that concur more with the time course of cognitive deficits." (PMID 38427092, 2024). "Regarding neuroinflammation, as induced in an animal model of pneumococcal meningitis, it was shown that chronic treatment with CBD (2.5, 5, or 10 mg/kg) significantly reduced TNF-α concentrations in the frontal cortex, preventing cognitive impairment." (PMID 38612615, 2024). "TNFα would be one of the main triggers of the pathways leading to alterations in the neurotransmission that lead to motor and cognitive impairment in hyperammonemia and hepatic encephalopathy." (PMID 39698415, 2024). "A recent systematic review and meta-analysis indicated the correlation between TNF-α and cognitive deficits in schizophrenia." (PMID 38429778, 2024). "The severity of cognitive impairment correlated with plasma IL-1β and TNFα levels and serum IL-6 levels." (PMID 39769285, 2024). "The possible mechanism underlying such cognitive impairment is the effect of inflammatory cytokines triggered by SARS-CoV-2 infection, mainly interleukin-6 (IL-6) and tumor necrosis factor-α (TNF-α)." (PMID 38336659, 2024). "This review analyzes the role of TNF-α and its increase in biological fluids in mild cognitive impairment, and Alzheimer’s disease (AD)." (PMID 38201258, 2023). "The production of proinflammatory cytokines, such as TNF‐α, IL‐6, and IL‐1β, further aggravates the neuroinflammatory response and leads to cognitive disorder." (PMID 37550899, 2023). "Several studies have shown that peripheral TNF-α levels are increased in patients with first-episode schizophrenia, and TNF-α-mediated immune-neurotoxicity contributes to cognitive impairment and the overall severity of schizophrenia." (PMID 37794014, 2023). "We found that cognitive impairment-like behaviors and TNF-α and IL-6 expression were higher in the hippocampus of aged mice than in those of young mice." (PMID 37872562, 2023). "Furthermore, several potential explanations for the association between BMD and cognitive impairment are as follows: First, bone mass loss may cause an increase in certain inflammatory markers, such as interleukin-6 and TNF-α, which promote the accumulation of inflammatory plaques in the brain." (PMID 37107586, 2023). "As we discussed, pro-inflammatory cytokines (IL-1β, IL-6, and TNF-α) play a role in neuroinflammation and cognitive impairment." (PMID 37631080, 2023). "Taken together, our results suggest that oleracones ameliorated cognitive impairment by blocking TNF-α-induced increases in VCAM-1, thereby reducing leukocyte infiltration to the brain and modulating brain inflammation." (PMID 36768379, 2023). "In another nephrectomized induced cognitive impairment rodent model, Klotho levels decreased in frontal cortex but not in hippocampus, accompanying with an increase in NF-κB and tumor necrosis factor-alpha levels." (PMID 37560310, 2023). "The levels of inflammatory cytokines (interleukin-1 beta (IL-1β), interleukin-6 (IL-6), interleukin-8 (IL-8), and tumour necrosis factor-alpha (TNF-α)) were measured using an assay method and compared with the subjective cognitive impairment." (PMID 39484178, 2023).
Cognitive impairment (continued). "Prophylactic inhibition of peripheral TNF-ɑ before surgery has been associated with reduced post-surgical inflammation, microgliosis, and cognitive impairment, highlighting the contribution of peripheral TNF signaling to postoperative brain changes." (PMID 37277738, 2023). "The primary evidence for this association derives from an initial study performed on the CSF of mild cognitive impairment (MCI) patients which demonstrated higher TNFα and tau protein levels and lower TGFß and Aß levels in MCI patients compared to controls." (PMID 38201258, 2023). "Animal treated with PTX shows an elevating level of inflammatory molecules (iNOS, TNF-α, IL-β), which leads to microglia polarization to M1 involved in cognitive impairment." (PMID 37631080, 2023). "The combination of NK41 and NK46 (4:1, NKc), which potently inhibited TNF-α expression in LPS-stimulated macrophages, additively alleviated cognitive impairment-like behaviors in 5xFAD-transgenic or aged mice." (PMID 37571319, 2023). "Increased serum IL-1β and TNF-α levels correlate with cognitive impairment and classical AD histopathologic brain lesions." (PMID 37760836, 2023). "Elevated TNF‐α was correlated to the occurrence of anxiety and cognitive impairment in AIS patients." (PMID 37878890, 2023). "The M1‐type macrophage further releases the proinflammatory cytokines such as IL‐1β, TNF‐α, and IL‐6, thereby resulting in brain damage and cognitive impairment." (PMID 34951130, 2022). "High levels of interleukin-10 (IL-10), interleukin-1 (IL-1), Tumor Necrosis Factor (TNF)-alpha have been observed in patients with cognitive impairment." (PMID 35889934, 2022). "The increased expression of iNOS (1.63-fold) and inflammatory factors such as TNF-α (1.85-fold) and IL-β (1.89-fold) compared to the control group suggests that M1 polarisation of microglia is involved in the process of cognitive impairment." (PMID 35944285, 2022). "The increment of major pro-inflammatory cytokines, including IL-1β and TNFα, plays a crucial role in neuroinflammation and cognitive impairment in AD." (PMID 35439990, 2022). "miR-122-5p inhibition prevents cognitive impairment, neuronal damage, microglia activation, and production of TNF-a, IL-6, and IL-1ß in hippocampus." (PMID 35955439, 2022). "The outcomes of this study support the use of LFD for cognitive disorders and highlight its underlying mechanism, targeting AChE, DNA-POL, NF-KB, and TNF-α, etc., for the first time." (PMID 36080247, 2022). "Scopolamine-treated mice have already been shown to have elevated levels of inflammatory cytokines (e.g., TNF-α, IL-1β, and IL-18) and cognitive impairment." (PMID 36294963, 2022). "We then compared the serum levels of soluble factors including 5-HT, GABA, BDNF, GR, CRH, IL-6 and TNF-α in preterm rats from the normal control group and cognitive impairment group." (PMID 36061856, 2022). "Accordingly, elevated serum levels of TNF-α in AD patients correlate with increased physical and cognitive impairment, and TNF-α is widely studied as a target for AD treatment." (PMID 36297637, 2022). "A previous study suggested that the levels of CRP, TNF-α, IL-1β, IL-6, and IL-8 in the peripheral blood of patients with mild cognitive impairment (MCI) were higher than those in the normal population." (PMID 36590060, 2022). "We found that SCH58261 inhibited microglial activation and decreased the levels of TNF-α, IL-1β and IL-6, ultimately alleviating cognitive impairment in CP mice." (PMID 36234803, 2022). "Pre-treatment with Gdcl3 effectively reduced the number of microglia (0.50-fold), inhibited the release of TNF-α (0.73-fold) and IL-β (0.56-fold), and improved cognitive impairment." (PMID 35944285, 2022). "There was a significant positive, very high linear correlation between the level of interleukin 6 (r = 0.788, *p < 0.05), TNFα (r = 0.817, *p < 0.05) in prefrontal cortex and cognitive impairment in diabetics mice in Y Maze Novelty Preference Test (NPT)." (PMID 35468904, 2022).
Cognitive impairment (continued). "Several epidemiologic studies have shown a rather consistent association between systemic inflammatory markers (i.e., high-sensitivity C-reactive protein, tumor necrosis factor-alpha, and interleukin-6) and dementia or cognitive impairment." (PMID 35160273, 2022). "It has been suggested that systemic administration of TNF-α can induce cognitive impairment, while anti-TNF-α treatment yields favorable outcomes in diseases with cognitive decline due to neuroinflammation." (PMID 35603184, 2022). "Multivariate logistic regression showed that TNF-α (OR=2.882, P=0.004) and NIHSS score ≥5 (OR=1.009, P=0.004) were associated with high risk of cognition impairment." (PMID 35239774, 2022). "To further elucidate the effect of BTL-I on AlCl3-induced cognitive impairment in zebrafish, we assessed changes in the levels of several biochemical indicators (including IL-1β, TNF-α, GSH, AChE)." (PMID 35130930, 2022). "The presence of long-lasting increments in pro-inflammatory cytokines in the hippocampus, such as Il-6, IL-1β, and TNF-α, has led to the implication of neuroinflammation in brain aging and cognitive impairments." (PMID 35866081, 2022). "Again, numerous studies have identified elevated levels of TNF-α in biological fluids in patients with aging, mild cognitive impairment, AD and epilepsy." (PMID 35957121, 2022). "In AD, the activation of microglia caused by Aβ accumulation is followed by the synthesis and release of pro-inflammatory cytokines, including interleukin-1β (IL-1β) and tumor necrosis factor-α (TNFα), and ultimately leads to cognitive impairments." (PMID 35439990, 2022). "Simultaneously, other research does not find a strict positive correlation between the severity of positive symptoms, cognitive deficits and enhanced levels of proinflammatory cytokines, such as IL-6, IL-1β and TNF-α." (PMID 36139363, 2022). "Inflammation has been implicated as a trigger of ADHD, and gastrodin has been proved to have anti-inflammatory pharmacological effects, which can alleviate cognitive impairment by lessening TNF-α and IL-6 levels." (PMID 36133787, 2022). "More importantly, hyperforin treatment significantly reduced Aβ deposition, GFAP expression, levels of IFN-γ, IL-1β, IL-6, and TNFα, and improved performance in behavioral tests, suggesting reversal of cognitive deficits." (PMID 35077394, 2022). "Together these data indicate a major role for TNF acting on TNFR1 in mediating cognitive impairment in neurodegenerative disease and suggest TNF as a therapeutic target." (PMID 35110639, 2022). "TNF levels are elevated in cerebrospinal fluid and plasma in aging, mild cognitive impairment, and in patients with AD." (PMID 36778591, 2022). "For this reason, further in-depth studies are needed in the future to clarify the correlation between serum TNF-α, iNOS as well as cognitive impairment and disease burden, so as to provide a reference for the early diagnosis and treatment of schizophrenia." (PMID 36246695, 2022). "Higher DII scores, also known as larger inflammatory potential of the diet, have been related to increased levels of inflammatory biomarker including IL-6, CRP, and TNF-α, thus linking to cognitive impairment." (PMID 36688153, 2022). "TNF-α induces astrocytes to A1-type (neurotoxicity) polarization, which impairs the number of synapses and ultimately leads to cognitive impairment." (PMID 36234803, 2022). "In this study, rats with CLP exhibited cognitive deficits 24 h after surgery, as well as severe inflammation in the CNS, manifested as increased expression of IL‐1R1, pNF‐κB, TNF‐α, and iNOS in microglial cells." (PMID 34837343, 2022). "Activated microglia secreted various neurotoxic and inflammatory factors, including IL-1β and TNF-α, ultimately leading to hippocampal neuroinflammation and hippocampus-dependent cognitive impairments." (PMID 35884806, 2022).